PIK3CA (phosphatidylinositol-4,5-bisphosphate 3-kinase catalytic subunit alpha)
Diseases named in the same sentence as PIK3CA in open-access papers (continued):
Sharing a sentence is not in itself a finding about the gene and the disease.
glioblastoma (103 papers, 2006 to 2026). The most malignant astrocytic tumor (WHO grade IV). "PIK3CA and PTEN mutations have been commonly reported in glioblastoma, though the PIK3CA and PTEN mutations are typically mutually exclusive." (PMID 39666263, 2025). "PIK3CA activating mutations have been associated with earlier recurrence and shorter survival in adult glioblastoma." (PMID 37533228, 2023). "Relevant studies have found that the activation mutation of PIK3CA is related to the early recurrence and poor prognosis of glioblastoma." (PMID 36065261, 2022). "The phosphatidylinositide 3-kinase (PI3K) pathway is frequently overactivated in glioblastoma due to PIK3CA mutations, loss of phosphotase and tensin homolog (PTEN) gene function, and amplification of epidermal growth factor receptor (EGFR) gene expression." (PMID 34899305, 2021). "Among low-grade CNS tumors, PIK3CA mutations have been described in rosette-forming glioneuronal tumors although they also occur in glioblastoma." (PMID 34193285, 2021). "Following these mutations, KRAS and PIK3CA activate their downstream signaling pathways out of control and cause immoderate cell division and survival in glioblastoma cells." (PMID 35194440, 2021). "In conclusion, despite the association with younger age, PIK3CA activating mutations are associated with earlier recurrence and shorter survival in adult glioblastoma." (PMID 31036078, 2019). "Here, we found that PIK3CA-activating mutations are associated with early recurrence and poor prognosis in glioblastoma." (PMID 31036078, 2019). "This study indicates that PIK3CA-activating mutations identify a subset of glioblastomas associated with younger patient age, early progression, and propensity to present with widespread disease." (PMID 31036078, 2019). "Phosphoinositide 3 kinase signaling pathway activation has been demonstrated in different types of human cancers, including glioblastoma, because of gain-of-function mutations in PIK3CA or loss of PTEN." (PMID 31013819, 2019). "We demonstrated that PIK3CA-activating mutations were associated with clinically-apparent increased invasiveness and/or CNS dissemination in patients with newly diagnosed glioblastoma." (PMID 31036078, 2019). "Activating mutations in PIK3CA gene are observed in 6–15% of glioblastomas, although their clinical significance is largely undescribed." (PMID 31036078, 2019). "The frequency of PIK3CA mutations in glioblastoma ranges from 4.3 to 26.7% due to diverse detection approaches and different sample sizes." (PMID 29326882, 2017). "In fact PIK3CA were one of the most mutated genes in various cancers like breast, colon, glioblastomas and so forth." (PMID 29228676, 2017). "Knockdown of PIK3CA (encoding p110α) significantly inhibits cell viability and motility in medulloblastoma and glioblastoma cells." (PMID 27176481, 2016). "These and the D54 glioblastoma line were sequenced for PIK3CA mutations using published primer sequences." (PMID 22064833, 2011). "PIK3CA mutations are common in glioblastoma but rare in low-grade astrocytomas." (PMID 40103938, 2025). "PIK3CA mutations have been reported in between 5 and 30%; this variation in the range can be attributed to different methodologies for analyzing mutation frequency in glioblastoma." (PMID 40564017, 2025). "It has been reported that 6–15% of glioblastomas contain activating mutations in the PIK3CA." (PMID 37370767, 2023). "Pik3ca also interacts with Lrp8, a gene related to the onset of neuropsychiatric diseases, such as schizophrenia, Mapk8, a gene associated with reduced apoptosis in glioblastoma cells, and Sorl1, which is decreased in AD brains by regulating Aβ accumulation." (PMID 36614117, 2022). "The objective of this study was to examine whether PIK3CA mutations are associated with a specific clinical phenotype in glioblastoma." (PMID 31036078, 2019). "PIK3CA mutations were observed in 26 of 291 (8.9%) glioblastomas in this cohort." (PMID 31036078, 2019).
glioblastoma (continued). "Therefore, the interactions between PIK3R1 mutation, TERT promoter mutation and PIK3CA mutation in adult glioblastoma clinical characteristics remain to be determined." (PMID 31036078, 2019). "Genome-wide sequencing of 91 glioblastomas revealed a 6.6% mutation rate in the PIK3CA gene." (PMID 29326882, 2017). "Constitutive G protein signalling may provide an explanation as to why PIK3CA mutations are relatively common in glioblastoma (9% in the TCGA database) while PIK3CB mutations are rare (1% in the TCGA database)." (PMID 28051998, 2017). "It is proved that mutation of PIK3CA occur in significant number of human glioblastoma multiforme." (PMID 23768168, 2013). "Therefore, we sought to determine whether somatic mutations in PIK3CA are associated with a distinct phenotype in patients with newly diagnosed glioblastoma." (PMID 31036078, 2019). "In the PI3K pathway, there was minimal cooccurrence of PIK3CA/3R1 and PTEN mutations (8.3%, P < .01), especially in glioblastoma." (PMID 39164213, 2025). "The first was based on the observation of KAT6A-induced TRIM24-mediated PIK3CA mRNA expression in glioblastoma." (PMID 40676628, 2025). "NF1 alteration (HR: 1.28), PIK3CA/3R1 alteration (HR: 1.25), CDKN2A/B loss (homozygous or heterozygous, HR: 1.21), and increasing age (HR: 1.03) negatively impacted survival for glioblastoma." (PMID 39164213, 2025). "Amongst these, IDH, PDGFR, and PIK3CA alterations characterize proneural glioblastoma, EGFR amplification occurs in classical glioblastoma, and NF1, PTEN, and NFκB mutations predominate in mesenchymal subtypes." (PMID 33396284, 2020). "Glioblastomas, a cancer class with a dismal long-term survival rate even with therapy, often have PTEN or PIK3CA mutations, AMPK activation, and large areas of necrosis at diagnosis." (PMID 32111826, 2020). "PFS of the patients with PIK3CA mutant glioblastoma (6.1 months) was significantly shorter than that of patients with the wildtype counterpart (9 months) (p = 0.008), while OS was not significantly different (median 13.1 months vs. 13.3 months, p = 0.40)." (PMID 31036078, 2019). "PIK3CA mutant glioblastoma often presented with widespread tumor dissemination relative to PIK3CA wildtype tumors." (PMID 31036078, 2019). "Given the known prognostic impact of IDH1 mutation on survival, we investigated the association of PIK3CA mutation with PFS and OS after excluding 12 IDH1 mutant glioblastomas." (PMID 31036078, 2019). "We found a significant association between PIK3CA mutation and more disseminated disease at diagnosis, as 6 of 13 (46.2%) PIK3CA mutant glioblastomas presented with dissemination compared to 16 of 144 (11.1%) PIK3CA wildtype tumors (p = 0.004)." (PMID 31036078, 2019). "Recently, recurrent somatic mutations in PIK3CA and PIK3R1 were identified in 6–15 and 10% of glioblastomas, respectively, which were accompanied by activated PI3K signaling." (PMID 31036078, 2019).
glioblastoma (continued). "Future studies should focus on clarifying the role of PIK3CA/p110α in glioblastoma using patient-derived primary glioblastoma cells in conjunction with orthotopic glioblastoma models or genetically engineered mouse glioblastoma models." (PMID 29326882, 2017). "MET amplification, PIK3CA mutations and amplification, ERBB2 mutations and amplification of CDK4 and CDK6 have been implicated in glioblastoma." (PMID 25256166, 2014). "Key members of the gene network,including vascular endothelial growth factor A (VEGFA),epidermal growth factor (EGF), and the catalytic subunitA of phosphatidylinositol-4,5-bisphosphate-3-kinase(PIK3CA), have been identified as important genetic markersof glioblastoma involved in angiogenesis." (PMID 39944803, 2024). "Mutations of PIK3CA, the gene encoding the p110α subunit of PI3K, or mutations of PIK3R1, the gene encoding the p85 regulatory subunit of PI3K, have been demonstrated in approximately 15% of patients with glioblastoma." (PMID 35022057, 2022). "Abrogation of PIK3CA could inhibit tumor cell proliferation, migration, and invasion in glioblastoma." (PMID 34367282, 2021). "Patients with PIK3CA mutant glioblastoma may require additional consideration in treatment planning and clinical trials." (PMID 31036078, 2019). "PIK3CA mutant (solid) and PIK3CA wildtype (dashed) glioblastoma patients depicted." (PMID 31036078, 2019). "Additional studies investigating the role of PIK3CA mutants in glioblastoma are therefore needed." (PMID 29326882, 2017). "In the same study, we knocked down PIK3CA/p110α in a panel of glioblastoma cell lines and found that loss of PIK3CA/p110α failed to both inactivate AKT and block the survival of A172, U87MG, SF295, and U251 glioblastoma cells." (PMID 29326882, 2017). "A total of 13 mutations of PIK3CA within these specific domains were identified in anaplastic oligodendrogliomas, anaplastic astrocytomas, glioblastoma multiforme, and medulloblastomas, whereas no mutations were identified in ependymomas or low-grade astrocytomas." (PMID 19384426, 2007). "Although in glioblastoma, KAT6A controls PIK3CA gene expression through TRIM24 binding to this gene promoter, in this study, TRIM24 promoted cell survival by associating to PI3Kα protein, thereby increasing its stability." (PMID 40676628, 2025). "This interaction leads to the activation of PIK3CA transcription, consequently promoting the PI3K/AKT signalling cascade and contributing to the progression of glioblastoma." (PMID 39778006, 2025). "KAT6A acetylates histone H3, activating PIK3CA transcription, thereby enhancing the PI3K/AKT signalling pathway and promoting glioblastoma development." (PMID 39778006, 2025). "In glioblastoma, KAT6A expression increases PI3Kα levels through the binding of TRIM24 to H3K23Ac in the PIK3CA gene promoter." (PMID 40676628, 2025). "Our progression model for glioblastoma has PTEN and PIK3CA together in the first layer of the driver tree." (PMID 36469540, 2022). "After miR‐218 overexpression in glioblastoma cells, we observed a decrease in the expression levels of GBM oncogenes such as PIK3CA, ROCK1, LAMC1 and ICAM1." (PMID 35702951, 2022). "Within the remaining 145 IDH1 wildtype glioblastoma patients, the difference in PFS between PIK3CA mutant and PIK3CA wildtype tumors was statistically significant by Wilcoxon test (p = 0.02) and was a trend to significance by log-rank test (p = 0.11)." (PMID 31036078, 2019).
glioblastoma (continued). "In combination with temozolomide or carmustine, small interfering RNAs (siRNAs) of PIK3CA and AKT3 substantially reduced the viability of T98G glioblastoma cells." (PMID 29326882, 2017). "Those genes include EGFR, PDGFRA, FGFR3, PIK3CA, MDM4, CDKN2A/B, PTEN and are all members of the core alterated pathways in glioblastoma controlling key phenotypes such as proliferation, apoptosis and angiogenesis." (PMID 25679508, 2015). "shRNA-mediated knockdown of either the PIK3CA or PIK3R1 gene resulted in reduced proliferation, migration, and invasion in glioblastoma cell lines, and in the case of the PIK3R1 gene these effects are independent of the Akt pathway." (PMID 22064833, 2011). "The reliance on several dysregulated—and often redundant—signaling pathways, including EGFR, PIK3CA, PDGF, and NF-κB, has been well-characterized in glioblastoma, and cross-talk between these have likely contributed in large part to the historical failures of targeted therapy." (PMID 33498872, 2021). "However, KAT6A mRNA levels are increased in glioblastoma samples compared to normal brain tissue, and KAT6A and has been shown to promote glioma cell proliferation via upregulation of PIK3CA expression and subsequent activation of PI3K/Akt signaling." (PMID 31914141, 2020). "Unlike these, the mutations in SEGA-like glioblastoma occurred in the context of other genetic aberrations present in high-grade neoplasms, including in the CDKN2A/B, PIK3R1, PIK3CA and EGFR genes." (PMID 31258848, 2019). "Notably, while both PIK3CA and PIK3R1 knockdown significantly reduces FAK activity in D54 glioblastoma cells, only reduction in PIK3R1 expression results in statistically significantly slowed cell migration, supporting the only partial role played by FAK signaling in GBM cell motility." (PMID 22064833, 2011). "KNS42 glioblastoma cells, by contrast, contained no genuine amplifications, but instead its highly rearranged genome harboured low-level copy number gains at loci such as 3q26 (PIK3CA), and hemizygous deletions at known tumour suppressor loci such as 13q14 (RB1)." (PMID 19365568, 2009). "Interestingly, tumors lacking PIK3CA mutations often harbored mutations in PIK3R1, with significant occurrences in UCEC (31%) and glioblastoma multiforme (GBM) (11%)." (PMID 38920700, 2024). "Previous studies have shown that the human paediatric glioblastoma (WHO grade IV) KNS42 cells are wildtype for PTEN and PIK3CA, histone H3.3 (H3F3A) G34V mutant and have no expression of MGMT." (PMID 28704425, 2017).
lung adenocarcinoma (92 papers, 2007 to 2026). A carcinoma that arises from the lung and is characterized by the presence of malignant glandular epithelial cells. "For example, PIK3CA mutations are present in 1–2% of all lung adenocarcinomas and their constitutive activation in downstream pathways has been associated with drug resistance." (PMID 38994972, 2024). "In comparison, GRIN2A mutations have relatively higher prevalence in TCGA cohorts of lung adenocarcinoma, squamous cell carcinoma, or in cutaneous melanoma, and PIK3CA mutations, in lung adenocarcinoma and squamous cell carcinoma." (PMID 32014051, 2020). "Based on previous studies, PIK3CA mutation occurred more in lung squamous cell carcinoma with a frequency of 11.4% than in lung adenocarcinoma with a frequency of 2.8%." (PMID 32908885, 2020). "Here, we screened 230 Chinese patient samples of lung SCC and reported the rarity of two most ubiquitous mutations in KRAS and EGFR seen in lung adenocarcinoma, while PIK3CA mutations were relatively high when compared with lung adenocarcinoma." (PMID 31749831, 2019). "It is noteworthy that the rate of mutation of PIK3CA in these samples is relatively higher when compared with lung adenocarcinoma." (PMID 31749831, 2019). "EGFR, KRAS, HER2, BRAF, and PIK3CA mutations are these important genetic alterations in the targeted therapies of lung adenocarcinoma." (PMID 29518290, 2018). "PIK3CA mutations were detected at a six-fold higher frequency in cfDNA than lung adenocarcinoma tissues based on data in the cBioPortal for Cancer Genomics database." (PMID 29290998, 2017). "In contrast to prior studies, we identified a high frequency of PIK3CA mutations in post-therapy lung adenocarcinoma patients." (PMID 27304188, 2016). "In present study, we found that PIK3CA mutation occurred in approximately 2.8% of patients with lung adenocarcinoma in a cohort of Chinese patients." (PMID 27554588, 2016). "We explored the status of PIK3CA mutation and evaluated its genetic variability, treatment, and prognosis in patients with lung adenocarcinoma." (PMID 27554588, 2016). "The initial surgically resected lung adenocarcinoma showed wild type PIK3CA and EGFR c.2573T > G (p.L858R) mutation." (PMID 27734950, 2016). "In this study, PIK3CA mutation was screened from 810 lung adenocarcinoma patients and its frequency, treatment and prognosis was evaluated, in order to enrich the understanding of PIK3CA as a driver gene in NSCLC treatment." (PMID 27554588, 2016). "With a frequency range of 2–5%, PIK3CA mutation occurred more in squamous cell carcinoma than lung adenocarcinoma." (PMID 27554588, 2016). "Although the receptor kinase genes were much less frequently mutated in lung SQCC than in lung adenocarcinoma, PIK3CA and PTEN were commonly altered in lung SQCCs in the present study." (PMID 26503331, 2015). "3.0% (34/1117) patients harbored mutations in PIK3CA, accounting for 2.7% (22/807) of lung adenocarcinomas, and 3.9% (12/310) of squamous cell carcinomas." (PMID 24533074, 2014). "Our earlier study, as well as other studies, found that PIK3CA mutations were more common in squamous cell lung cancer than in lung adenocarcinoma." (PMID 25348872, 2014). "The prevalence of EGFR, BRAF, and PIK3CA mutations in lung adenocarcinomas was 6 (13/234), <1 (1/156), and 2% (2/132), respectively." (PMID 17487277, 2007). "Mutations in EGFR, ATM, and PIK3CA may provide new ideas for predicting TMB in lung adenocarcinoma patients." (PMID 35521981, 2022). "In 152 patients with stage IV lung adenocarcinoma, 10 were detected with PIK3CA mutations (6.58%)." (PMID 33997043, 2021). "In addition to EGFR, ALK-EML4 fusion, KRAS mutation, HER2 amplification, and PIK3CA mutation were also found in lung adenocarcinomas with MLCs." (PMID 34234879, 2021). "Mutations of the PIK3CA gene occur in lung adenocarcinoma tissue, but is a relatively seldom event." (PMID 34625038, 2021).